IL1B (interleukin 1 beta)
Diseases named in the same sentence as IL1B in open-access papers (continued):
Sharing a sentence is not in itself a finding about the gene and the disease.
influenza (continued). "Furthermore, this GO analysis indicated that genes associated with the antiviral response to influenza (e.g., Ifi27l2a, Isg20, Oas1a, Isg15, Ifit1, Oasl1, and Ifit3) were strongly enriched in mice vaccinated with WIV alone as compared with mice vaccinated with WT IL-1β or CD8α ALN-1." (PMID 32714571, 2020). "Serum concentration of IL-6, IL-1β, TNFα, IFNγ were found elevated in cases of HAdV, RSV, and influenza AURTIs compared to age-specific normal values." (PMID 33066100, 2020). "Our results illustrate that, in response to a primary influenza infection, there was diminished bacterial clearance and heightened production of pro-inflammatory cytokines, such as IL6 and IL1β." (PMID 32545261, 2020). "RAW264.7 macrophage cells and primary murine alveolar macrophages also showed increased IL-6, TNF-α, IFN-β, and/or IL-1β production in the presence of 1-methyltryptophan another IDO pharmacological competitive inhibitor, following influenza infection." (PMID 32267860, 2020). "When analysing all influenza-infected mice (2A3 and 1A8 treated), there was a significant correlation between the levels of BALF mCRAMP and airway neutrophils or IL-1β." (PMID 29079611, 2018). "To address this question, we stained lymph nodes on day 2 of influenza infection with antibodies against CD169, IL-1β, IL-18, and IL-33." (PMID 29249358, 2018). "FP7 led to a significant reduction in influenza-induced gene expression for TNF-α, IL-1β, IFN-β, KC (P < 0.01), IL-6, and RANTES (P < 0.05)." (PMID 28106157, 2017). "We were particularly interested in IL-2, IL-12p70, IFN-γ, IL-1β, IL-10, IL4, and TNF-α, given their involvement in the immune response during influenza infection and also given the phenotype of the response upon vaccination." (PMID 28792466, 2017). "Previous studies have reported a correlation between IL-1β and IL-6 overexpression and some clinical, radiological and immunological findings, such as pneumonia and ARDS, in both children with seasonal influenza and murine models." (PMID 26657940, 2015). "Following murine infection with influenza, aged DC show impairments in NLRP3 inflammasome/caspase-1 activation, and downstream IL-1β and IL-18 production, suggesting age-related impairments in DC pathogen sensing and/or innate activation." (PMID 22862959, 2012). "Induction of the proinflammatory cytokines IL-1β, IL-6, IL-8 and IFN-α mRNA levels were induced due to influenza H7N1 infection in the lungs of these chickens." (PMID 21314972, 2011). "In particular IL-1β has been shown to be a critical component of host defense against influenza in murine lung infection, induced in response to viral activation of the NLRP3 inflammasome, with influenza stimulating increased IL-1β production by macrophages." (PMID 22031815, 2011). "The concentrations of the cytokines IL-1β, IL-6, TNF-α, CXCL1,CXCL2, CCL5, IFN-γ and IL-12p40 were evaluated in lung homogenates ofcontrol and Influenza infected mice." (PMID 21079759, 2010). "LAIV (like wild-type influenza) expresses M2 protein in infected cells and therefore activates NLRP3 inflammasomes, resulting in the production of the potent inflammatory cytokines IL-1β and IL-18." (PMID 39591131, 2024). "Empagliflozin treatment decreased the expression of the inflammatory cytokines IL-1β, IL-6, and CCL2; the percentage of inflammatory monocytes and inducible NO synthase–positive macrophages; and IFN response genes Stat1 and CXCL9 during influenza infection." (PMID 38112660, 2023). "In contrast, our results indicate that, in pigs, neither prior pH1N1 influenza exposure nor immunization with Ad-HA/NP with or without Ad-IL-1β confer heterotypic protection." (PMID 37153548, 2023). "Exposure to aerosols generated from VG/PG with and without nicotine caused greater influenza-induced production in the distal airspaces of the pro-inflammatory cytokines IFN-γ, TNFα, IL-1β, IL-6, IL-17A, and MCP-1 at 7 days post inoculation (dpi)." (PMID 36999019, 2023).
influenza (continued). "In fact, as Debisarun and colleagues highlight, influenza vaccinations modulate the responses against SARS-CoV-2, reducing IL-1β and IL-6 production while enhancing IL-1Ra release, and the cytokine storm due to dysregulated immune responses is well-known to underlie systemic SARS-CoV-2 damage." (PMID 35746506, 2022). "Likewise, bafilomycin A1, erythromycin, and clarithromycin were studied to impede the making of IL-1β, IL-6, IL-8, TNF-α, and intercellular adhesion molecule (ICAM)-1 in influenza and rhinovirus-modeled infections." (PMID 33937285, 2021). "In addition, hsa-miR-326, hsa-miR-15b-5p, hsa-miR-885, hsa-miR-122-5p, hsa-miR-133a-3p, and hsa-miR-150-5p showed high correlations to IL-6, IL-15, IL-17A, IL-1β, and monocyte chemoattractant protein-1 (MCP-1) with both strains of influenza." (PMID 33540650, 2021). "Influenza vaccination did not appear to have an immediate effect on macrophage inflammasome activity, although IL-1β levels were slightly elevated in unstimulated macrophages 24 h post-vaccination compared to baseline (161.27 vs 152.01 pg/ml, p = 0.01)." (PMID 35822051, 2021). "Moreover, influenza vaccination modulated the responses against SARS-CoV-2, reducing IL-1β and IL-6 production while enhancing IL-1Ra release." (PMID 34695164, 2021). "As such, the gut microbiome was reported to influence DC migration to draining lymph nodes and T cell priming during influenza infection by providing signals leading to pro-IL1β and pro-IL18 expression at steady state and inflammasome activation upon influenza infection." (PMID 33905460, 2021). "Proinflammatory cytokines such as interleukin-1β (IL-1β) and tumor necrosis factor–α (TNF-α) are both strongly induced shortly after PR8 influenza infection in mice, and, notably, COUP-TF2 expression is suppressed by these same cytokines in endometrial stromal cells." (PMID 33239293, 2020). "Similarly observed in influenza-pneumonia and CAP there was clear indication that IFN-γ downregulates the IL-1β level similar trend is observed in COVID-19 pandemic but further study is required at molecular level in future to draw this conclusion." (PMID 33634060, 2020). "First, alveolar macrophages were significantly more potent than neutrophils at producing IL-1β on a per-cell basis, due to a greater induction of IL-1β and NLRP3 mRNA (and both populations were present in comparable numbers in the airways of influenza-infected mice)." (PMID 29079611, 2018). "Conversely, the second signal driving inflammasome activation and IL-1β release is lacking, with levels of cleaved caspase-1 (generated through inflammasome activation) markedly reduced in the lungs of influenza-infected mice after neutrophil depletion." (PMID 29079611, 2018). "Our data showed that a constitutive lack of IL-1β substantially impaired neutrophil infiltration into the airways and lung during influenza-induced exacerbations of chronic lung inflammation." (PMID 24918427, 2014). "Because a positive correlation between local cytokine concentration and lung pathology has been observed, we hypothesize that local production of IL-1β, IL-8 and TNF-α is involved in the induction of lung lesions during influenza infection." (PMID 24846450, 2014). "We found significantly reduced expression levels of IL-17A in lung homogenate in the absence of IL-1β, in both non-infected as well as influenza-infected LPS/elastase exposed mice." (PMID 24918427, 2014). "In conclusion, our data showing the expression patterns of NLRP3, IL-1β and TNF-α in H9N2 AIV infected mice further support that NLRP3 inflammasome protein play a crucial role in the physiological and pathological processes of influenza infection." (PMID 25547136, 2014). "To determine the possible impact of ST2 on pulmonary inflammation during influenza infection, we measured lung levels of cytokines (IFN-γ, TNF-α, IL-1β, IL-6, IL-10, IL-33, IL-13, IL-5) and chemokines (KC, MIP-2) at 3, 8 and 14 days following influenza inoculation." (PMID 23483993, 2013).
influenza (continued). "Thus, NS1, an influenza virulence factor that inhibits the RIG-I/type I IFN pathway, strongly modulated the IL-1β response in lung epithelial cells and in ferrets." (PMID 23592984, 2013). "On the other hand, in survivors the most important outputs showed no upregulated genes in hepatitis, upregulation of il1b both in influenza and measles and tnfa upregulation in measles." (PMID 24069208, 2013). "In macaques, Mtb and PR8 influenza induced strong TNF production, whereas Schu S4 induced IL-1β." (PMID 21789257, 2011). "In mice, significant levels of TNF and IL-1β were observed following infection with Mtb and Fuj/02 influenza, whereas no cytokines were detected following exposure to PR8 or Schu S4." (PMID 21789257, 2011). "To further investigate the effect of rm-APC treatment on the inflammatory response in severe influenza, we determined pulmonary levels of various cytokines (TNF-α, IL-1β, IL-6, IL-10, IL-12p70, IFN-γ) and chemokines (KC, MIP-2) in lung homogenates obtained 48 and 96 hours after infection." (PMID 20398279, 2010). "It was shown earlier, that proinflammatory cytokines (IL-1β, IL-6, TNF-α, IFN-α) and microglial reactivity were increased, while neurotrophic (BDNF, NGF) and immunomodulatory (CD200, CX3CL1) factors were decreased in the hippocampus of influenza infected adult mice." (PMID 41567998, 2025). "Influenza may also influence the development of affective disorders in adults through cytokines released during the immune response, such as interferons, TNF-α, IL-1β, and IL-6, which activate the kynurenine pathway, producing neurotoxic metabolites." (PMID 39206043, 2024). "Since CD8+ T cells, monocyte-derived macrophages, and Krt8hi progenitors accumulate within dysplastic areas after influenza infection, we tested whether macrophage-derived IL-1β is a negative regulator of AT2 to AT1 trans-differentiation." (PMID 38077031, 2023). "Finally, we examined the expression of Il-1β and cleaved GSDMD in lung and its relationship to macrophages (CD163+) and alveolar epithelial cells (cytokeratin+) in uninfected macaques and those with lethal influenza by immunohistochemistry." (PMID 35271686, 2022). "In this study, we observed that B.dorei administration decreased production of several cytokines (IL-1β, IL-6, IL-10,TNF-α, MCP-1, and IP-10) in lung and serum induced by influenza infection, which may alleviate excessive inflammatory response and ameliorate immunopathologic damage." (PMID 35154087, 2021). "Therefore, MPL fails to induce maturation of IL‐1β and consequently fails to achieve efficient vaccination against influenza infection." (PMID 32428336, 2020). "However, the levels of these DAMPs in the BALF of mice in our influenza model were unaltered by neutrophil depletion, and administration of inhibitors that abrogated these pathways failed to diminish IL-1β release." (PMID 29079611, 2018). "However, it is interesting that the four pro-inflammatory cytokines induced by Pam2-ODN 4 h after treatment (IL-1α, IL-1β, IL-6, and TNF) are also the first four pro-inflammatory cytokines induced from respiratory epithelial cells in native influenza infections." (PMID 22299046, 2012). "However, we could not observe any significant secretion of IL-1β or activation of the inflammasome pathway in the LN following influenza vaccine administration." (PMID 31824481, 2019). "Serum concentrations of proinflammatory cytokines, including IL-1β, ΤΝF-α, and IFN-γ, were low or below the limit of detection in most study participants irrespective of treatment group or influenza type." (PMID 37289541, 2023). "LPS administration 4 days after influenza infection resulted in a synergistic increase in TNF-α, IL-1β, and IL-6 concentrations in lung tissue, but not in plasma." (PMID 29978355, 2018). "This neutrophil dependence for IL-1β release was not seen with other cytokines, with BALF IL-6 and TNF-α levels comparable between influenza-infected control and neutrophil-depleted mice." (PMID 29079611, 2018).
influenza (continued). "Multiple inflammasomes can be involved in IL-1β activation, including NLRP3, NLRP1, NLRC4, AIM2, IFI16 and RIG-I, however because GC B cells are not directly infected by influenza infection, we examined NLRP3 and AIM2 as they are activated by stimuli likely to be present in GC B cells." (PMID 40825032, 2025). "No appreciable levels of IL-1β, MIP-1α or MIP-1β were detected from the basolateral or apical compartments of AIV or human influenza infected NHBE cells (data not shown); however, AIVs induced differential apical and basolateral expression patterns of IL-1a, IL-8, IP-10, MCP-1, and RANTES over time." (PMID 21731666, 2011).
endometriosis (191 papers, 2006 to 2026). The growth of functional endometrial tissue in anatomic sites outside the uterine body. "MR analysis was conducted to assess the causal relationship between IL1B expression and endometriosis." (PMID 41239476, 2025). "Endometriosis-associated angiogenesis is driven, among others, by proangiogenic cytokines such as IL-1β, IL-6, IL-8, and IL-17A." (PMID 39859551, 2025). "Elevated endometriosis risk was associated with lower expression of IL1B in two myeloid cell types (monocytes, dendritic cells) and elevated expression in three data sets." (PMID 40938538, 2025). "These carotenoids can downregulate the expression of pro-inflammatory cytokines such as IL-6 and IL-1β, which are heavily implicated in the inflammatory milieu of endometriosis." (PMID 39968397, 2025). "Our Mendelian randomization analysis further supports a causal relationship between genetically predicted IL1B expression and endometriosis risk, aligning with prior GWAS-based observations." (PMID 41239476, 2025). "Increased serum levels of TNF-α, IL-6, and IL-1β, released from disease-associated macrophages, were observed in patients with endometriosis-induced infertility, creating a feedforward loop to aggravate endothelial cell activation." (PMID 40130159, 2025). "MR analysis supported a potential causal relationship between IL1B and endometriosis (MR-Egger OR = 2.66, P < 0.05)." (PMID 41239476, 2025). "This study provides mechanistic insights into the potential role of triclosan in endometriosis development, highlighting IL1B as a possible causal mediator." (PMID 41239476, 2025). "The number and strength of associations for IL1A, and the myeloid‐specific associations for IL1B are further evidence to link these genes to endometriosis risk." (PMID 40938538, 2025). "Another study revealed upregulated genes like EGF and IL-1β in endometriosis, associated with focal adhesion and calcium signaling, implicating them in endometriosis pathogenesis." (PMID 39108650, 2024). "These cells are then activated by the cytokines secreted by the macrophages, including TNFa, Il12, IL6, and Il1b, which cause their proinflammatory anti-endometriosis activation." (PMID 39253270, 2024). "IL-1β can aggravate endometriosis-associated pain and inflammation by increasing the secretion of brain-derived neurotrophic factor in eutopic endometrial stromal cells at the mRNA and protein level." (PMID 37893241, 2023). "Similar to the previous experiments with estradiol, we analyzed ESCs after treatment with TNF-α and IL-1β, the representative cytokines associated with endometriosis, alone and in combination with DNG." (PMID 36428561, 2022). "Tumor necrosis factor alpha (TNF-α) and interleukin 1 beta (IL-1β) are proinflammatory factors that have been associated with the progression of endometriosis." (PMID 36428561, 2022). "The peritoneal fluid and serum of patients with endometriosis and adenomyosis were found to have elevated levels of inflammatory cytokines, including IL-6, IL-8, IL-1b, IFN-γ, and TNF-α, which was associated with natural killer (NK) cell dysfunction." (PMID 35022045, 2022). "The IL1B*2-allele homozygote was found in a very low frequency (< 5%) in both groups and in all four stages of endometriosis." (PMID 36028805, 2022). "The prevalence of TNF*2-allele heterozygotes (p = 0.025; OR 3.8), TNF*2-allele (p = 0.029; OR 3.4), IL1B*2-allele heterozygotes (p = 0.044; OR 2.69) and its carriage rate (p = 0.041; OR 2.64) in endometriosis stage IV was higher than the CTR group." (PMID 36028805, 2022). "The associations analysis suggests an approximate threefold increased risk for women with endometriosis stage IV with IL1B*2-allele heterozygote genotype and a tendency to a twofold increased risk with IL1B*2-allele [p = 0.056; OR 2.09; 95%CI (1.04–4.02)]." (PMID 36028805, 2022).